IFITM4P (interferon induced transmembrane protein 4 pseudogene)
Synonyms: dJ377H14.5
Gene: Transcribed processed pseudogene on chromosome 6 (29,750,729 to 29,751,148, reverse strand). Ensembl gene ENSG00000235821.
Diseases named in the same sentence as IFITM4P in open-access papers:
IFITM4P is named in the same sentence as 13 diseases in open-access papers, as found by Europe PMC text mining. Sharing a sentence is not in itself a finding about the gene and the disease. The quoted sentences say what the papers report.
asthma (1 paper, 2024). "Cluster 5, which includes genes at 6p22.1 (HLA-A, HCG4P5, HLA-T, MOG, TRIM26, HCG9, IFITM4P), demonstrated further connections between JIA and a subset of autoimmune/inflammatory traits (i.e., type 1 diabetes, asthma, eczema, and severe COVID-19 or rheumatoid arthritis)." (PMID 39175752, 2024).
leukoplakia (1 paper, 2022). A white patch or plaque on a mucous membrane that cannot be characterized clinically or pathologically as any other disease. "The histopathological diagnosis also confirmed leukoplakia on the dorsal tongue and local early invasive tongue SCC in the 4NQO group; FISH staining showed that IFITM4P in the 4NQO group was stronger, while mice in the PBS group were not stained." (PMID 35051616, 2022).
melanoma (1 paper, 2022). A malignant, usually aggressive tumor composed of atypical, neoplastic melanocytes. "Next, to test the influence of IFITM4P on anti-PD-1 therapy, we utilized an anti-PD-1 mAb to treat C57BL/6 mice inoculated with melanoma (B16F10) cells overexpressing the control vector or IFITM4P." (PMID 35051616, 2022).
squamous cell carcinoma (1 paper, 2022). A carcinoma arising from squamous epithelial cells. "To evaluate the effect of IFITM4P on the development of OSCC from OL in mice induced with 4NQO, we used a modified C57/B6J mouse tongue leukoplakia/squamous cell carcinoma (SCC) model." (PMID 35051616, 2022).
tongue leukoplakia (1 paper, 2022). "We found that LPS accelerated the development of tongue SCC from tongue leukoplakia in vivo, elevated IFITM4P expression, induced a tumor-immunosuppressive effect through PD-L1 upregulation, and increased the therapeutic sensitivity of PD-1 mAb therapy." (PMID 35051616, 2022). "Furthermore, to verify the influence of IFITM4P on anti-PD-1 therapy, we utilized PD-1 mAb to treat mouse early tongue leukoplakia induced with 4NQO + LPS or 4NQO alone." (PMID 35051616, 2022). "PD-L1 and IFITM4P staining of tongue SCC from mice in cages III and IV were stronger than that of tongue leukoplakia from mice in cage II, while the normal tongue mucosa from mice in cage I was not stained." (PMID 35051616, 2022).
tumor (2 papers, 2022). "Taken together, these results demonstrated that LPS accelerated tongue carcinogenesis in the mouse model, elevated IFITM4P expression, and induced a tumor-immunosuppressive effect through PD-L1 upregulation." (PMID 35051616, 2022). "The IFITM4P group showed a significantly higher tumor volume compared with the vector group (∗p < 0.05)." (PMID 35051616, 2022). "Interestingly, the PD-1 mAb therapy had a significantly better tumor-inhibitory effect in the IFITM4P group than on the control group (∗p < 0.05)." (PMID 35051616, 2022). "IFITM4P enhances the interaction of KDM5A with the PTEN promoter, resulting in reduced transcription of PTEN and upregulated PD-L1 expression, thus activating the therapeutic sensitivity of PD-1 in the nucleus of tumor cells." (PMID 36601121, 2022).
IFITM4P also shares sentences with these, for which no sentence is quoted: breast tumor (1 paper); cancer (1); COVID-19 (1); eczema (1); rheumatoid arthritis (1); tongue SCC (1); type 1 diabetes (1).